RNU7-41P (RNA, U7 small nuclear 41 pseudogene)
Synonyms: U7.41
Gene: Small nuclear RNA gene on chromosome 14 (34,845,300 to 34,845,360, reverse strand). Ensembl gene ENSG00000251726.
Homologues: Orthologues: macaque U7 (97% identical). Paralogues in human: RNU7-13P (93% identical), RNU7-6P (93% identical), RNU7-11P (92% identical), RNU7-25P (92% identical), RNU7-2P (92% identical), RNU7-8P (92% identical), RNU7-18P (90% identical), RNU7-22P (90% identical), RNU7-3P (90% identical), RNU7-28P (89% identical), RNU7-60P (89% identical), RNU7-85P (89% identical), and 142 more.